KRAS (KRas proto-oncogene, GTPase)
Diseases named in the same sentence as KRAS in open-access papers (continued):
Sharing a sentence is not in itself a finding about the gene and the disease.
tumor (continued). "This study design allows to exclude a possible “generic” effect of statins on survival, because patients with a KRAS wildtype tumor and patients in the arm without cetuximab were also included in the analysis." (PMID 25375154, 2014). "We next asked whether ZNF304 and its corepressors silenced CIMP marker genes in other KRAS-positive human CRC cell lines and tumor samples." (PMID 24623306, 2014). "PCR-based DNA sequencing analysis of the patient’s tumor specimen revealed no EGFR, BRAF, KRAS, NRAS, PI3KCa, or c-kit mutations." (PMID 25126591, 2014). "The manufacturers of both the Therascreen KRAS and Cobas KRAS and BRAF assays state that less than 5% mutant DNA can be detected using 100 ng gDNA isolated from FFPE tissue samples with at least 10% tumor cells on the slide." (PMID 23991070, 2013). "This is in contrast to our current amphotropic retroviral transduction system, which maintains paradiploidy after stable KRASG12V expression, but limits KRAS expression to ~6-fold, and fails to tumor formation in SCID mice." (PMID 24386371, 2013). "Emerging clinical data suggest that intra-tumor let-7a expression correlates with tumor response and overall survival in metastatic colorectal cancer patients receiving epidermal growth factor (EGFR) targeting agents in both KRAS wild-type and mutant populations." (PMID 23936455, 2013). "Additionally, KRAS and RREB1 are targets of miR-143/145, demonstrating a feed-forward mechanism that potentiates RAS signaling-mediated PDAC tumor progression." (PMID 24040120, 2013). "In all, 460 patients with KRAS wild-type tumours who had not previously received EGFR therapy were randomly allocated to irinotecan (230 patients) or IrPan (230 patients), and these form our primary population for this report." (PMID 23725851, 2013). "Although there is now widespread agreement that the presence of a KRAS mutation indicates that a patient is unlikely to respond to anti-EGFR therapy, there is some concern around the area of tumour heterogeneity." (PMID 23356214, 2013). "The expression levels of EREG in the tumours of responding and non-responding patients by KRAS gene status is depicted in a waterfall plot." (PMID 23374602, 2013). "High mRNA levels of AREG predicted for longer survival in patients with KRAS wild-type (median survival 33 vs. 15 months, p=0.0005), but not in KRAS mutant tumours (median survival 22 vs. 17 months, p=0.64)." (PMID 23374602, 2013). "With regard to the carryover of genetic mutations from patient NSCLC tissues to mouse xenograft tissues, data from our study showed that genotypes are consistent between the original patient tumor and the corresponding xenograft tissue in all ten models for EGFR and KRAS status." (PMID 23842453, 2013). "By contrast, in KRAS-wild type tumours EREG failed to significantly predict for response to therapy (OR 2.2, 95% CI 0.83-5.86, p=0.11)." (PMID 23374602, 2013). "Adding panitumumab to irinotecan did not improve the overall survival of patients with wild-type KRAS tumours." (PMID 23725851, 2013). "Also, to dissect out the benefit of anti-oxidant rich seaweed polyphenols in targeting tumor progression markers, first, we investigated the transcriptional regulation of Bcl2, EGFR, PDGFA, VEGF, AKT, TERT, kRas and FGF in PC cells." (PMID 23613993, 2013). "However, only EGFR mutations were tested in 112 patients, neither KRAS nor EGFR mutation test could not be done in 32 patients due to small amount of tumor DNA, and 11 cases who were not tested for both exon 19 and 21 EGFR mutations were classified as unknown mutation status." (PMID 23724098, 2013). "The clinicopathological factors of age, gender, pathological tumor size, nodal status, lymphatic permeation and blood vessel invasion and the EGFR and KRAS mutation spectra were compared between never and heavy smokers." (PMID 24179496, 2013).
tumor (continued). "The error rate was 2.6% for cell lines in similar tumor content conditions (false negative due to 5% samples excluded) suggesting that tissue fixation was not an obstacle to KRAS testing." (PMID 23935912, 2013). "In a total of 345 patients the tumor samples were adequate for both EGFR and KRAS analysis." (PMID 23922984, 2013). "Over all subsequent lines of therapy, 54 (24.7%) of the 219 patients with WT KRAS tumours had no subsequent therapy, 109 patients (49.8%) received anti-EGFR therapy, and 56 patients (25.6%) received no anti-EGFR therapy." (PMID 23174912, 2012). "Of these 5 tumours with loss of the 12p12.1 locus, 2 tumours harboured a KRAS mutation, and one tumour had a BRAF mutation, suggesting that the mechanism of gene copy number loss is independent of the KRAS and BRAF mutation status." (PMID 22804917, 2012). "Other studies have shown no prognostic effect of tumour KRAS status on survival in patients receiving combination chemotherapy with bevacizumab." (PMID 23174912, 2012). "Multivariate analysis established that the effect of KRAS was independent of other variable factors such as sex, tumour site or Dukes stage." (PMID 23174912, 2012). "OS was longer in patients with WT KRAS tumours who did not receive anti-EGFR therapy than in patients with MT KRAS tumours (26.9 months versus 20.2 months; HR: 1.48; 95% CI: 1.02–2.16; p = 0.0379)." (PMID 23174912, 2012). "A mutation in the BRAF oncogene occurs in approximately 10% of mCRC patients and is restricted to KRAS wild-type tumours, and was first shown to have a negative predictive value for anti-EGFR therapy." (PMID 22804917, 2012). "All these findings suggest that the high KRAS discordant rate of lung metastasis (32.4%) had not simply resulted from types of tumor tissue specimens (biopsied vs. resected) or less sensitive analytic methods performed at our institute." (PMID 22876814, 2012). "Semi-quantitative reverse transcription-polymerase chain reaction (RT-PCR) and Western blotting were performed to detect expression of mRNA and protein, respectively, of RBM5, EGFR and KRAS in 120 paired non-tumor and tumor samples of NSCLC." (PMID 22537942, 2012). "Overall, patients with grade 2+ vs. grade 0/1 skin toxicity appeared more likely to respond to treatment, irrespective of tumour KRAS status, even though patients with MT KRAS tumours are not thought to benefit from panitumumab." (PMID 23020584, 2012). "Similarly, increased 1-year and 2-year survival was seen among those patients with KRAS wild-type tumours and high AURKA-CN compared with patients with KRAS wild-type tumours and low AURKA-CN (1 year: 96% vs 75% P<0.0001; 2 year: 93% vs 28% P<0.0001)." (PMID 22240781, 2012). "Furthermore, the reduced RBM5 protein expression correlated with smoking status, tumor stage and lymph node metastasis of NSCLC, while overexpression of EGFR and KRAS proteins correlated with tumor stage and lymph node metastasis of NSCLC." (PMID 22537942, 2012). "KRAS mutations (G12V and G13D) (n = 3) and the PIK3CA H1047R mutation (n = 1) were detected in FFPE tumor samples, but no mutations were found in any cpDNA samples." (PMID 23144797, 2012). "Therefore, 92% of ALK rearrangements in NSCLC are predicted to occur in patients whose tumours can be proven to be both EGFR and KRAS wild type." (PMID 22374459, 2012). "Patients with high AURKA-CN tumours had longer median OS (48.6 vs 18.8 months, P=0.01), with stronger trend among KRAS wild-type tumours (median OS not reached vs 18.8 months, P=0.003)." (PMID 22240781, 2012). "Several miR-143 targets, including DNMT3A and KRAS, and miR-145 targets including BNIP3, IRS, C-MYC, YES and STAT1, have been identified, indicating that miR-143 and 145 act as tumor suppressors to repress tumor proliferation or promote apoptosis." (PMID 22438992, 2012). "In all, 68% of tumour exhibited high AURKA-CN, and 29% had a KRAS mutation, without correlation between the two." (PMID 22240781, 2012).
tumor (continued). "In our previous work, we demonstrated that combined shRNA-mediated silencing of β-catenin and KRAS in CRC cells led to massive induction of apoptosis in vitro and suppression of tumor growth in vivo, while individually targeting either of the two pathways showed modest effects." (PMID 23227266, 2012). "In turn, macrophages enhanced Wnt signaling, proliferation and survival in both HCT116 and Hke-3 cells, demonstrating that signaling by oncogenic kRas in tumor cells does not impact their interaction with macrophages." (PMID 23029025, 2012). "We detected a similarly substantial overlapping between the KRAS and PIK3CA mutations, but all PIK3CA mutated tumours in the present study were non-responders." (PMID 21439039, 2011). "In 5 of the 25 lymph node metastases that we tested the KRAS status was not concordant with the primary tumour, which is consistent with the literature." (PMID 21364579, 2011). "A Kirsten ras sarcoma viral oncogene (KRAS) wild-type (WT) status of the tumor is necessary, but possibly not sufficient, for a response to anti-EGFR monoclonal antibody therapy." (PMID 21437184, 2011). "Furthermore, we demonstrated that discordance of test results between primary tumour and metastases cannot account for the failure rate of anti-EGFR therapy in patients with KRAS wild-type tumours." (PMID 21364579, 2011). "The absence of KRAS and BRAF mutations in our set of benign tumours is consistent with the paucity of somatic events observed in independent reports." (PMID 22163003, 2011). "Nevertheless, even among patients with KRAS wild-type tumours, the majority of patients do not respond to anti-EGFR therapy." (PMID 21364579, 2011). "Developing antibody incidences did not appear to be affected by tumor KRAS status (wild-type or mutant) or combination chemotherapy regimen (oxaliplatin- or irinotecan-based)." (PMID 22070868, 2011). "Although both KRAS 300/145 and KRAS 300/73 DII decreased with tumour progression (13- and 30-fold decrease, respectively), KRAS 300/145 DII remained more elevated than 300/73 DII (for instance the mouse #16 DII was 0.13 for the KRAS 300/145 ratio and 0.02 for the KRAS 300/73 ratio)." (PMID 21909401, 2011). "In particular, tissues for KRAS genotyping should contain an adequate percentage of tumor cells to avoid false negative results." (PMID 22216189, 2011). "In the primary tumor, we found that both ERBB2 and KRAS were heterogeneously amplified." (PMID 22014070, 2011). "Another theory that has been suggested for the lack of effect in KRAS wt samples, is heterogeneity within the tumor and between primary tumor and metastasis." (PMID 22272141, 2011). "Epidermal growth factor receptor (EGFR) and KRAS status were particularly critical for the choice of first-line targeted therapy of non-small cell lung cancer (NSCLC), while the primary tumor and metastases might be different in the EGFR and KRAS gene status." (PMID 20840818, 2010). "Moreover, functional studies in a KRAS mutant CRC murine model has confirmed MKP-3 high levels, and high MKP-2 and MKP-3 expressions have been described in human tumour biopsy samples from mutant KRAS CRC patients." (PMID 20234366, 2010).
tumor (continued). "The key strength of our study was that laboratories (with the exception of Agencourt) analyzed KRAS from tumor sections on glass slides rather than from DNA, and the results were consequently a closer mimic of clinical testing procedures." (PMID 20398393, 2010). "However, knocking down KRAS in HCT116 and NRAS in IPC298 led to a significant delay in tumor growth, indicating the requirement of KRAS in HCT116 and NRAS in IPC298 for tumor growth in vivo." (PMID 19492075, 2009). "In the CARO2 study which compared CapOxBev with and without cetuximab, patients whose tumor has MT type KRAS did worse which did reach statistical significance." (PMID 19386128, 2009). "In the two largest studies, no patients with KRAS MT tumors showed an objective tumor response to panitumumab." (PMID 19386128, 2009). "A single copy of chromosome 9, 13, 15, 18 and 22 was found in at least one EGFR tumor, no monosomy was found in the KRAS group." (PMID 18549475, 2008). "We evaluated the incidence of BRAF and KRAS mutations, high-frequency microsatellite instability (MSI-H), and the immunohistochemical status of p-MAPK in the nonserrated neoplasias (46 FDNs and 57 PNs)." (PMID 16404419, 2006). "Accordingly, LZTR1 has a tumor suppressor phenotype following CRISPR-mediated knockout in KRAS-dependent, but not RAS-independent, MM lines, and LZTR1 knockdown amplified KRAS protein expression in KRAS-dependent MM lines via decreased K48-linked ubiquitination of KRAS." (PMID 41542462, 2026). "Thus, DKK3 loss accelerates the earliest step of tumor initiation, whereas DKK3 induction can delay, but not abolish, KRAS‐mediated ADM, underscoring KRAS dominance." (PMID 41147409, 2026). "The genomic background of CRC, including alterations in KRAS, NRAS, PIK3CA, AKT1, BRAF, and the tumor’s MSI status, may modulate both the abundance and biological relevance of the immune regulators TIGIT and CD155, thereby affecting immune evasion and clinical outcome." (PMID 41596586, 2026). "Thus, in the adagrasib resistant SW1573 model harboring KRAS-G12C and CDKN2A homozygous loss, adagrasib and abemaciclib combination, but not adagrasib alone, mediated anti-tumor effects and survival prolongation." (PMID 40317086, 2025). "Interestingly, in human LUAD as well as other tumor types carrying KRAS mutations, the presence of CIC mutations correlates with the lack of KRAS oncogene amplification (Fig. EV4D,E)." (PMID 41219537, 2025). "In our patient, the tumor was negative for the common BRAF, KRAS, and NRAS mutations." (PMID 41169288, 2025). "In subgroups like KRAS or BRAF, which have demonstrated higher response rates to ICIs treatment, combining TKI with immunotherapy could potentially enhance therapeutic synergy, modulating the tumor microenvironment." (PMID 39859299, 2025). "The translational rationale is straightforward: KRAS-mutant LGSOC often relies on chronic MAPK signaling for proliferation and survival, so simultaneous and persistent suppression of RAF → MEK signaling should produce deeper and more durable tumor control than MEK inhibition alone." (PMID 41584508, 2025). "Emerging evidence suggests that not all KRAS‐driven tumours are biologically equivalent; subtype‐specific features—such as co‐occurring mutations, metabolic reprogramming and immune‐suppressive stromal interactions—play critical roles in shaping therapeutic vulnerabilities and resistance mechanisms." (PMID 41025426, 2025). "Unlike EGFR‐mutant tumours, which exhibit relatively uniform biology and high therapeutic sensitivity, KRAS‐mutant NSCLC is characterised by profound molecular heterogeneity, divergent co‐mutational profiles (e.g., STK11, KEAP1), and dynamic crosstalk with the tumour microenvironment (TME)." (PMID 41025426, 2025). "Whether KRAS inhibition leads to CCA tumor regression is unknown, partly due to the lack of conditional animal models." (PMID 41332325, 2025).
tumor (continued). "Furthermore, we observed RAFi-driven activation of GCN2-ISR in tumour cells with wild type BRAF, mutant BRAF, mutant KRAS and immortalised MEFs with no ERK pathway mutation." (PMID 41249187, 2025). "However, when injected alone into nude mouse models, CAFs did not form tumors, indicating that the acquisition of mutant KRAS proteins alone was insufficient to confer invasive and proliferative abilities similar to those exhibited by the tumor cells." (PMID 39810420, 2025). "However, only two of over 21,000 tumor-distinct clones identified and none of the shared, clonally dominant sequences in our cohorts matched those reported to be mutant KRAS specific." (PMID 39789181, 2025). "Recently, STK11/LKB1 co-mutated with KRAS (KL subtype) were found to be resistant to anti-PD1 treatment due to the presence of a strong association between STK11/LKB1 genomic alterations and lack of PD-L1 expression on tumor cells." (PMID 39932765, 2025). "In preclinical studies using a KRAS mutant non-small-cell lung cancer (NSCLC) xenograft model, NBF-006 demonstrated significant tumor suppression and prolonged survival, with 70–80 % of the administered dose being internalized by tumor tissues and was well tolerated by the animal models." (PMID 40390497, 2025). "This suggests that while the bystander effect mediated by MSC-derived DEG-KRAS delivery is functionally active, it may not be sufficient to fully eliminate KRAS-dependent signaling in the tumor context." (PMID 41322195, 2025). "However, our IDH‐mutant tumours had no excess of CMS3, a CRC subtype associated with mucinous cancers and KRAS mutations (OR = 0.25; 95% CI = 0.04–1.49; p = 0.15)." (PMID 40545636, 2025). "Furthermore, the effects of SIAIS562055 on SOS1 degradation and pERK inhibition in MIA PaCa-2 tumor tissues correlated with the in vitro results, as confirmed by the significant suppression of SOS1/KRAS/ERK signaling and induction of caspase-3 cleavage upon treatment with SIAIS562055." (PMID 39437162, 2025). "Interestingly, the KRAS and NOXA genes have gained significant attention in cancer research due to their crucial roles in tumor metabolism and apoptosis regulation, respectively, as both of them are fundamental to tumor development and progression." (PMID 40913040, 2025). "On the other hand, NCDB provides detailed information on tumor characteristics and treatment aspects not available in SEER, such as microsatellite instability, KRAS mutations, palliative care details, unplanned hospital readmissions, and 30‐day mortality rates following surgery." (PMID 40444529, 2025). "The following nongenetic factors related to pancreatic steatosis could serve as activating events for oncogenic KRAS signaling, contributing to pancreatic steatosis-induced PDAC, with current hypotheses focusing on the roles of inflammatory pathways and the tumor microenvironment." (PMID 39991930, 2025). "Consequently, there are currently no studies reporting the impact of KRAS inhibitors on the tumor microbial microenvironment." (PMID 40485603, 2025). "Finally, T-cytotoxic lymphocytes (CD8+) and tumor-associated macrophages (CD163+) were evaluated in samples with EGFR and KRAS mutations, ALK rearrangements and LUAD with no genetic findings." (PMID 40809430, 2025).